MITF (melanocyte inducing transcription factor)
Diseases named in the same sentence as MITF in open-access papers (continued):
Sharing a sentence is not in itself a finding about the gene and the disease.
melanoma (continued). "The total ERK1/2 signal was similarly heterogeneous in both Grey and non-grey samples (71.2 ± 17.4 vs. 50.5% ±13.0 in MITF+ cells of the respective melanoma type)." (PMID 25413220, 2014). "Thus, the corequirement for MITF and BRG1 in the regulation of ML-IAP expression is highly correlated with enhanced survival following UV irradiation in multiple melanoma cell lines." (PMID 23480510, 2013). "In addition, reduced MITF expression levels would occur when POU3F2 expression is elevated, and this would also correspond to instances in vivo in melanoma tissues when pigment production is reduced." (PMID 24062982, 2013). "Depletion of BRM in BRG1-negative SK-MEL-5 cells was sufficient to block proliferation, whereas the growth of BRG1/BRM-expressing RPMI7951 melanoma cells, which are exceptionally MITF-negative, was not affected." (PMID 23349796, 2013). "In the comparative analysis between non-oncogenic melanocytes and melanoma cell lines, no differential expression of MITF was found by the gene level analysis." (PMID 23594586, 2013). "We show that MITF-correlated miR-211 expression levels are mostly but not always reduced in a panel of 11 melanoma cell lines and in primary and metastatic melanoma compared to normal melanocytes and nevi, respectively." (PMID 24039954, 2013). "Thus, additional factors are likely involved in the regulation of ML-IAP in melanoma cells because both MITF and BRG1 are expressed at similar levels in induced melanocytes as in melanoma cells that express higher levels of ML-IAP." (PMID 23480510, 2013). "We have also previously reported that PAX3 does not transcriptionally activate MITF in melanoma cells, an observation contrary to that outlined in a number of contemporary melanoma research papers." (PMID 24062982, 2013). "QRT-PCR experiments showed that naïve 501mel melanoma cells exposed to the secretome of melanoma cells rendered senescent by MITF silencing exhibited an increased level of SNAIL1, TWIST1, Fibronectin1, N-Cadherin (CDH2) mRNAs whereas MITF and E-Cadherin (CDH1) transcripts were markedly decreased." (PMID 24344100, 2013). "Furthermore, we previously showed that knockdown of MITF expression in NZM6 and NZM15 melanoma cell lines led to an almost 4-fold increase in the migration rates of the cells." (PMID 24062982, 2013). "While sometimes difficult to distinguish, clear cell sarcoma can be differentiated from malignant melanoma by examining a combination of primary tumor location, dissemination, growth speed, staining with MART-1 and MITF, and FISH detection of EWS gene rearrangement." (PMID 24274261, 2013). "The expression of OPN, IGF1, TGFß2, and survivin was not reported previously to be MITF-dependent in melanomas." (PMID 23349796, 2013). "Our data indicate that MITF and BRG1 containing SWI/SNF complexes coordinately promote transcriptionally permissive chromatin structure on one MITF target, the ML-IAP promoter in melanoma cells." (PMID 23480510, 2013). "P-CREB and MITF are present in control melanoma cells that did not receive norartocarpetin treatment." (PMID 24325567, 2013). "Our earlier investigations are, to our knowledge, the only comprehensive investigations systematically addressing this notion, demonstrating that PAX3 does not transcriptionally activate MITF in melanoma cells." (PMID 24062982, 2013). "The results agree with an earlier study reporting that Axl-positive melanoma cells do not express MITF." (PMID 23755070, 2013). "On the other hand, MITF directly binds to the promoter region of diaphanous homolog 1 (DIAPH1, DIA1) gene and activates its transcription, resulting in inhibiting the invasiveness of melanoma by activation of actin polymerization." (PMID 22046555, 2011). "To further assess whether ATF2 regulation of MITF is SOX10-dependent in melanocytes and melanoma cells, we coexpressed SOX10 in shATF2-expressing cells." (PMID 21203491, 2010).
melanoma (continued). "In contrast, MiTF expression is not detectable in parental and selected melanoma cells cultured with C2C12 cells plated at high density." (PMID 20174581, 2010). "MITF and SOX10 mRNA levels in melanocytes and melanoma cell lines following ATF2 KD." (PMID 21203491, 2010). "Unlike other biomarkers in melanoma, MITF is expressed at various levels in almost all melanoma specimens." (PMID 20163701, 2010). "MITF-Mdel was widely expressed in melanocytes, melanoma cell lines and tissues, but almost undetectable in non-melanoma cell lines or PBMC from healthy donors." (PMID 20163701, 2010). "Melanoma cell line 1973 carries only the MITF-Mdel isoform and not the wild-type MITF; whereas melanoma cell line 624 carries both isoforms." (PMID 20163701, 2010). "Notably, about 4/12 melanoma lines revealed increase in both SOX10 and MITF expression upon KD of ATF2." (PMID 21203491, 2010). "Collectively, out of 18 melanoma lines we found that 8 (44%) retained similar negative regulation of MITF by ATF2 as observed in the melanocytes." (PMID 21203491, 2010). "In murine melanoma cells, TGF-β decreases pigmentation by decreasing the stability of tyrosinase mRNA and protein, as well as decreasing the level and the activity of MITF." (PMID 20130821, 2009). "As in melanoma cells, BRAF and MITF are both essential for melanocyte proliferation, but in contrast to melanoma cells, MITF expression does not depend on BRAF expression or MEK/ERK signalling in melanocytes." (PMID 18628967, 2008). "One possible explanation for the lack of MITF regulation by WTBRAF is that unlike melanoma cells, melanocytes do not express BRN2." (PMID 18628967, 2008). "The tumor‐suppressive miR‐107, frequently downregulated in melanoma, exerts its anti‐proliferative and anti‐invasive effects by targeting POU3F2,113 a transcription factor that interacts with both SOX10 and MITF in melanocytes, thus indirectly affecting the SOX10‐MITF regulatory network." (PMID 40458894, 2025). "Regardless of genomic classification, melanoma can switch from a proliferative and differentiated phenotype (marked by high MITF expression) to an invasive and dedifferentiated phenotype (characterized by low MITF and neural crest stem cell markers such as NGFR)." (PMID 40806546, 2025). "Compared to the regulation without miR‐155, a negative regulator of melanoma cell proliferation and survival, the leaky MITF transcripts are translated into proteins, resulting in a possible longer retention of tumor cells in aggressive phenotypes that favor tumor progression." (PMID 40458894, 2025). "Notably, MiTF staining was positive in a few melanomas that failed to stain for either HMB‐45, S‐100, TYR, or Melan‐A which are the most commonly used melanoma markers." (PMID 40509563, 2025). "From an immunohistochemical point of view, S-100 protein, HMB-45, Melan-A, SOX-10, and MiTF are usually positive (melanocytic line differentiation features) and recently also it was demonstrated the potential utility of negativity for PRAME in the differential diagnosis with melanoma." (PMID 40004764, 2025). "Our analyses were performed in only two melanoma cell lines, which may not capture the full heterogeneity of melanoma subtypes with distinct MITF- or SOX10-dependent phenotypic states." (PMID 41465475, 2025). "DANCR may play an essential role in melanoma downstream of MITF and c-MYC irrespective of tumour genomic status." (PMID 41336739, 2025). "This event directly up-regulates microphthalmia transcription factor (MiTF) pathway with downstream activation of the pathway involved in melanocytic differentiation and, notably, this translocation has not been documented in melanoma." (PMID 40004764, 2025). "To investigate this, we classified melanoma cell lines as either EP300/SOX10 co-amplified (>2 copies of both EP300/SOX10) or not co-amplified, treated them with the potent and specific p300 KAT inhibitor A-485, and probed for SOX10 and downstream SOX10 target genes, such as MITF and DCT." (PMID 38994683, 2024).
melanoma (continued). "Although the relationship between MITF and PD-L1 in cancer cells remains unclear, some evidence suggests that MITF is critical for nonresponse to ICI therapy in melanoma patients." (PMID 38351314, 2024). "Additionally, NOTCH, WNT, and SOX family members, as well as MITF, Paired Box 3 (PAX3), and Forkhead Box D3 (FOXD3) are essential for early neural crest development and have been reviewed in the context of initiating EMT in melanoma." (PMID 38426087, 2024). "Similarly, in melanoma, TRIM63 and CAPN3 are a direct target of MiTF, wherein TRIM63 mRNA expression was positively correlated with MiTF transcription factor and knockdown of MiTF decreased TRIM63 levels." (PMID 38393424, 2024). "We therefore propose that identifying expression levels of MITF/SOX10, AXL/EGFR/ERBB3 prior to initiation of treatment may contribute to predicting treatment response to MAPK inhibitors and perhaps advice on drug combination strategies in melanoma." (PMID 36251678, 2023). "Although one of the best-studied pathways involved in melanoma cell plasticity is represented by canonical Wnt signaling-dependent up-regulation of MITF expression, this effect has not been observed in our experiments, since β-catenin expression was not depleted in TG2 KO clones." (PMID 37898636, 2023). "However, down-regulation of MITF protein and mRNA expression was only observed in the human melanoma cell line M14 but not in other cell lines." (PMID 37575275, 2023). "Undifferentiated melanomas are defined as completely lacking conventional histopathological and immunohistochemical melanocytic differentiation (negative for the five commonly used melanoma markers—MelanA, MiTF, HMB45, S100, and SOX10) and displaying a “vimentin-only” phenotype." (PMID 37373134, 2023). "Conclusion: α-Mangostin suppresses melanoma cells growth, migration and invasion, and synergistically enhances the anti-tumor effect of chemotherapy, whose mechanism may be mediated through inhibiting Ras, PI3K and MITF." (PMID 37575275, 2023). "A-alum-1 decreased the slightly induced MITF mRNA and protein expression levels after 24 h of α-MSH treatment, suggesting that A-alum-1 decreases levels of tyrosinase mRNA and protein in the α-MSH-induced B16F1 melanoma cells via suppressing intracellular MITF mRNA and protein levels." (PMID 37834109, 2023). "For instance, in colon cancer and melanoma, it acts as a tumor suppressor by deacetylating histidine triad nucleotide-binding protein (HINT) 1 and enhances its binding efficacy with oncogenic transcription factor β-catenin and microphthalmia transcription factor (MITF)." (PMID 35496046, 2022). "Thus, melanoma cells secrete negative immunomodulatory agents whose release is increased upon MITF silencing." (PMID 35956175, 2022). "MITF is expressed in about 80% of human melanomas (since it is not frequently expressed in desmoplastic melanomas); it is amplified in 10% of primary and 20% of metastatic cutaneous melanomas and its expression correlates with decreased 5-year overall patient survival." (PMID 35682684, 2022). "In addition, small interfering RNA-mediated MITF silencing in melanoma cells significantly reduces melanin content by inhibiting TYR, TYRP-1, and MC1R, which indicates that the transcriptional activation of MITF is a promising strategy for treating hypopigmentation." (PMID 36235048, 2022). "Considering the tumour heterogeneity between melanoma and GC, together with our results, it is reasonable to speculate that MAPK1 promotes GC proliferative/metastatic properties via phosphorylation of MITF (Serine73), enhancing its activity instead of stability." (PMID 36268034, 2022). "Furthermore, pharmacological inhibition of the MITF signaling pathway using small molecule ML329 reduced cell viability in MITF-dependent melanoma (SK-MEL-5 and MALME-3M) cells without affecting the viability of A375 cells, a MITF-independent cell line." (PMID 35159049, 2022).
melanoma (continued). "However, we noted that while MITF expression was similar in primary tumors and metastases, a number of well‐characterized MITF target genes (e.g., TYR, TYRP1, MELANA, PMEL) were significantly more highly expressed in primary melanomas than in metastases." (PMID 35771179, 2022). "Therefore, MITF and SOX10 are melanocyte-specific transcription factors that regulate pigmentation and contribute to protection against UV radiation, but also play significant roles in promoting aspects of melanoma tumorigenicity." (PMID 35323214, 2022). "Importantly, MMDR is described in three different BRAF mutant melanoma cells, regardless of their transcriptional phenotypic MITF/AXL signature." (PMID 34957688, 2022). "Although not yet fully defined, MITF has roles in melanoma development and progression." (PMID 35682684, 2022). "However, malignant melanoma cells will survive persistent stress thanks to distinct "cancerous" signaling pathways (e.g. MEK) and transcription factors that regulate the expression of so-called "survival genes" (e.g. HIF, MITF)." (PMID 33990669, 2021). "However, in high-OXPHOS melanomas, MITF is not suppressed by HIF1α but is promoted by the mammalian target of rapamycin (mTOR), leading to the transcription of PGC1α, a transcriptional coactivator which induces the expression of different OXPHOS genes." (PMID 33498757, 2021). "Additionally, MITF expression of the xenograft tumors was independent of the initial MITF expression status of the injected cell line, indicating that melanoma cells can switch dynamically between different phenotypes." (PMID 34071193, 2021). "Moreover, MITF expression expanded multivesicular bodies (MVBs) and LE, without affecting the number of lysosomes in the C32 melanoma line, enhancing Wnt signaling and the proliferation of these cells." (PMID 34356645, 2021). "If SOX10/SOX11 double positivity might serve as an indicator of lymphatic invasion, triple SOX11/SOX10/MITF gene interaction might induce genesis of a subtype of MMs which do not express positivity for the conventional pan-melanoma cocktail." (PMID 33801642, 2021). "For example, poorly invasive MITFhigh melanoma cells can cooperate with highly invasive MITFlow cells to enable invasion, and both phenotypes are present at the invasive front, indicating that MITF expression does not necessarily have to be downregulated for successful melanoma invasion." (PMID 34071193, 2021). "Since our study showed a link between HuR and MITF and that HuR is known to regulate HIF-1α and HIF-1α-regulated target genes such as VEGF, it will be of interest to investigate the role of HuR in melanogenesis and melanogenesis regulated tyrosinase in melanoma." (PMID 33418925, 2021). "Similarly, prolonged culturing of melanoma cells in media lacking the amino acid glutamine leads to decreased MITF expression levels also mediated via upregulation of ATF4." (PMID 34071193, 2021). "Interestingly, the MRD melanoma cells in zebrafish express little to no MITF protein and have increased expression of ECM genes." (PMID 33438577, 2021). "Among the various kinds of melanocyte markers, we especially focused on MITF and HMB45 (also known as PMEL17) because MITF is thought to be a master gene for cells of the melanocyte lineage, and HMB45 is an antibody that recognizes melanoma- and melanocyte-specific antigens." (PMID 34432824, 2021). "Notably, several consequences of MiTF depletion in melanoma were recapitulated by FANCA or FANCD2 depletion despite the maintenance of MiTF expression; inversely, their overexpression limits the consequence of MiTF depletion on melanoma cell behaviour." (PMID 33723374, 2021). "Since in vivo tumors contain a mix of melanoma and nonmelanoma cells, we also asked whether any correlation with PAX3 or MITF was observed in 53 melanoma cell lines grouped according to four different melanoma phenotypes distinguished by SOX10, SOX9, and MITF expression." (PMID 34819350, 2021).
melanoma (continued). "Due to the phenotype switching model in melanoma as one main model for heterogeneity and plasticity, we screened the EnrichR analysis for the enrichment of relevant transcription factor target genes in the CHEA database, namely genes with MITF and POU3F2 (Brn2) binding site, respectively." (PMID 34439267, 2021). "Finally, it may be reasonable to develop CAR-T cells targeting proteins highly expressed in dedifferentiated melanoma, such as AXL, whose expression is clearly inversely correlated with that of MITF." (PMID 33276788, 2020). "However, we found that MITF plays a suppressive role in lung cancer progression and is a favorable prognostic marker for overall survival in NSCLC, which is contrary to the role of MITF in melanoma." (PMID 33293474, 2020). "Most intriguingly, the expression of CD271 defines a subpopulation of melanoma cells lacking the expression of typical antigens like MART-1, HMB45, melanoma-associated antigens (MAGE) and regulators of proliferation or melanin synthesis e.g., MITF or TYR." (PMID 32878000, 2020). "Interestingly, also MITF inhibition, via MAPK pathway, leads to glycolysis in melanoma cells." (PMID 32528879, 2020). "However, a recent study indicated that melanoma cells with genetic ablation of SMAD7 exhibited a dual invasive/proliferative phenotype without suppression of MITF." (PMID 33293474, 2020). "Intra-vital imaging of an engineered mouse melanoma cell line has additionally shown that the motile, invasive cells leaving the site of the primary tumor have high expression of BRN2 while lacking pigmentation markers, suggesting a loss of MITF expression." (PMID 32632141, 2020). "PME promoted melanin production, tyrosinase activity, and the expression of melanogenic genes, such as MiTF and tyrosinase in B16F10 cells, as previously reported in mouse B16 cells, rat dermal papilla cells, human foreskin melanocytes, and human melanoma SK-MEL-18 cells and zebrafish." (PMID 32714420, 2020). "To answer, we reanalyzed the set of genes that were (i) reciprocally responding to the transition of melanoma invasion types; (ii) upregulated after the PLX4032 treatment along with MITF; (iii) had an LTR5_Hs in their neighborhood (10 Kb from Transcription Start Site (TSS)) that are bound by MITF." (PMID 33202765, 2020). "Co‐treatment of MITF negative melanoma cells with RANKL and BRAFi conferred no survival advantage." (PMID 31323160, 2020). "In order to determine whether MITF and TFEB are able to influence each other’s expression, we investigated the effects of transiently overexpressing the two individual factors on their expression in 501Mel and Skmel28 human melanoma cell lines." (PMID 32881934, 2020). "In our study, BEA and BEA G1 concurrently inhibited the activation of ERK1/2, JNK, p38 MAPK, NF-κB p65, STAT3, and MITF in A375SM melanoma cells, suggesting that the natural compounds may effectively inhibit aggressive melanoma by targeting multiple oncogenic molecular pathways." (PMID 32340351, 2020). "MITF regulates invasion of melanoma cells through negative feedback loop with Notch signaling." (PMID 32626712, 2020). "MITF is also known to regulate a number of genes involved not only in melanocyte differentiation and pigment formation, but also in the survival, growth, and metastasis of melanoma cells." (PMID 32340351, 2020). "ACF can induce a decrease in MITF expression in melanoma cells even in the absence of ATF4." (PMID 33396270, 2020).